ICAM1 (intercellular adhesion molecule 1)
Diseases named in the same sentence as ICAM1 in open-access papers (continued):
Sharing a sentence is not in itself a finding about the gene and the disease.
inflammation (continued). "Inhibition of ICAM-1 by AIA significantly decreased the bladder inflammation grade and mast cell counts, which was accompanied by a reduction of purinergic receptors (P2X2/P2X3), prostaglandin E2, EP1/EP2 receptors, TNF-α, NK1R, and ICAM-1." (PMID 27782122, 2016). "ICAM-1 and TNF-α have been demonstrated to play a major role in the nerve inflammation associated with DPN." (PMID 26539228, 2015). "Activation of renal endothelial cell ICAM-1 and the contributions of leukocytes in the pathophysiology of renal inflammation in DN have been previously documented." (PMID 24040012, 2013). "A variety of cytokines, including IL-6, IL-8, IL-10 and ICAM-1, are considered to participate in lung inflammation, which is closely related to the development of BPD." (PMID 23935746, 2013). "Until now, much of the focus on ICAM-1 in lung inflammation has been related to the membrane-bound form and its role in leukocyte trafficking." (PMID 21247482, 2011). "In the context of intestinal inflammation, mucosal microvascular endothelial cells overexpress cell adhesion molecules (CAMs) including P-selectin, ICAM1, and VCAM1 on both sides of the canal lumen to recruit leukocytes, which trigger a more severe inflammatory response." (PMID 37287987, 2023). "eNAMPT is also involved in vascular inflammation by increasing the expression of endothelial cell adhesion molecules (intercellular adhesion molecule 1 [ICAM-1] and vascular cell adhesion molecule 1 [VCAM-1]) in endothelial cells, which boost the adhesion of monocytes." (PMID 37915565, 2023). "VCAM-1 and ICAM-1 are related to the pathophysiological process of vascular inflammation." (PMID 35620579, 2022). "Based on the results of in vivo and in vitro experiments, macrolides improve macrophage phagocytosis and downregulate expression of intercellular adhesion molecule-1 and IL-8, eventually inducing neutrophil apoptosis and alleviating neutrophilic airway inflammation in individuals." (PMID 36276929, 2022). "Although the role of epithelial ICAM-1 is less well established than endothelial ICAM-1, which functions as the major adhesion receptor for leukocyte rolling-adhesion and transendothelial migration, studies suggest that airway epithelial ICAM-1 likely plays an important role in lung inflammation." (PMID 33690714, 2021). "IL-18 also increases the expression of vascular cell adhesion molecule 1 (VCAM-1) and intercellular adhesion molecule 1 (ICAM-1) in endothelial cells and cardiomyocytes, thus increasing leukocyte recruitment into the injured myocardium and amplifying cardiac inflammation." (PMID 34707513, 2021). "Our results suggest that ICAM-1 may play a critical role in bladder inflammation in severe NBC and may be used as a novel therapeutic target in non-bacterial bladder inflammation such as BPS/IC." (PMID 27782122, 2016). "Furthermore, our studies demonstrate that proteases in poultry dust induce, in addition to IL-8 and IL-6, other genes implicated in lung inflammation such as IL-1β, CCL2, ICAM-1, PTGS2 and TLR4 in alveolar as well as bronchiolar epithelial cells." (PMID 27770804, 2016). "Activation of PPARγ can decrease endotoxemic-induced, lipopolysaccharide-induced, and hemorrhage-induced acute pulmonary inflammation and injury through inhibition of neutrophil accumulation, ICAM-1 expression, and proinflammatory cytokine (IL-6, IL-1β) production." (PMID 27556035, 2016). "ICAM-1 is required for firm adhesion of neutrophils to the endothelium and for initiation of transendothelial neutrophil migration during vascular and systemic inflammation." (PMID 25097454, 2014). "However, the significant decrease in percentage of ICAM-1+ lung ECs in C57BL/6 mice receiving a CBD treatment prior to irradiation supports the hypothesis of an attenuated vascular lung inflammation induced by CBD." (PMID 39518030, 2024).
inflammation (continued). "Additionally, previous reports have shown that elevated circulating TMAO could induce low-grade chronic systemic inflammation through various inflammatory proteins (IL-6, ICAM1, COX2, LPS etc.)and contribute to metabolic dysfunction." (PMID 38982486, 2024). "In addition, excessive intake of cholesterol may cause vascular inflammation, and pro-inflammatory cytokines such as TNF-α and IL-6 may stimulate the expression of adhesion molecules and chemokines such as VCAM-1, ICAM-1, and fibronectin in aorta tissue." (PMID 24364887, 2013). "Cochlear inflammation contributes to NIHL, and intercellular adhesion molecule-1 (ICAM-1) is a marker for noise-induced cochlear inflammation." (PMID 38791192, 2024). "Elevated levels of E-selectin, ICAM-1, VCAM-1, and serpin E1 (PAI-1) are indicative of endothelial inflammation and injury." (PMID 38600563, 2024). "Subsequently, the expression of molecules crucial for the development of vascular inflammation, including IL-6, MMP-2, MMP-9, VCAM-1, and ICAM-1, was measured." (PMID 34336088, 2021). "Previous research has shown that IL-6, IL-1β, MCP-1, NF-κB, TNF-α, ICAM-1 and VCAM-1 are all involved in the process of vascular inflammation." (PMID 34830730, 2021). "We next assessed the biological relevance of LFA-1, ICAM-1 and ICAM-2 expressions on the development of ILC2-dependent AHR and airway inflammation." (PMID 33193309, 2020). "A similar effect was observed with BCP in a mouse model of cisplatin-induced renal inflammation, whereby pretreatment with oral BCP significantly attenuated renal ICAM-1 mRNA expression." (PMID 31766439, 2019). "MAPK signaling has been implicated in the transcription of various proinflammatory cytokines (e.g., eotaxin-1, MCP-1, and IL-8) and adhesion molecules (e.g., ICAM-1 and VCAM-1), which contribute to a worsened airway inflammation." (PMID 26783416, 2016). "Inflammatory factors such as ICAM-1, VCAM-1, TNFα, IL-6, and CRP have key roles in mediating vascular inflammation and blocking RAAS negatively modulates the levels of these inflammatory molecules." (PMID 24804145, 2014). "Canonical steps of neutrophil recruitment that mediate crawling and arrest, such as LFA-1/ICAM1 or Mac-1/ICAM1 neutrophil–endothelial cell interactions, are not required in remote lung inflammation." (PMID 40048367, 2025). "Next, we investigated the role of ROS in PMs-induced pulmonary inflammation, pre-administration of NAC (3–5 mg/mouse) before intratracheal instillation of PMs (200–350 μg/mouse, 7 days) significantly attenuated PMs-induced ICAM-1 and IL-6 expression in lung tissues by immunohistochemical staining." (PMID 29329563, 2018). "Acute vascular inflammation was induced in the rabbits by placing a silastic collar around the left carotid artery for 24 hours, the carotid collar significantly increased the endothelial expression of VCAM-1 and ICAM-1." (PMID 30327711, 2018). "The findings that hapten-induced colonic eosinophilic inflammation is critically dependent on ICAM-1 and that IL-4 provoked aggregation of human mast cells by promoting LFA-1/ICAM-1 adhesion molecules may help to explain our current observation." (PMID 27445435, 2016). "This antibody however did not interfere with human ICAM-1 binding to its ligand on human T cells and further it had no non-specific effects on cell recruitment in models of airway inflammation induced by mechanisms independent of human ICAM-1." (PMID 23935498, 2013). "The human ICAM-1 specific antibody 14C11 could therefore prevent HRV16 entry and replication as well as induction of airway inflammation in vivo." (PMID 23935498, 2013). "Although we would not expect 14C11 to interfere with mouse LFA-1 - mouse ICAM-1 interaction it was still necessary to demonstrate the specificity of 14C11 by performing studies in a model of airway inflammation that did not require human ICAM-1." (PMID 23935498, 2013).
inflammation (continued). "Peripheral monocytes attach to the damaged brain ECs expressing intercellular adhesion molecule-1 (ICAM-1) and vascular cell adhesion molecule-1 (VCAM-1), which are the downstream factors of the kappa-light-chain-enhancer of activated B cells (NF-κB) observed during acute CNS inflammation." (PMID 34445248, 2021). "However, this increase in adhesion was markedly inhibited by the depletion of YAP/TAZ using siRNA in endothelial cells, suggesting that YAP/TAZ is critically involved in endothelial inflammation by regulating the expression of the adhesion molecule VCAM1 and ICAM1." (PMID 30388809, 2018). "Besides these observed effects, ICAM-1 is furthermore required for ILC2 homeostasis and efficient activation in the lungs, as absence of ICAM-1 specifically on ILC2s significantly inhibits IL-5 and IL-13 secretion and development of airway inflammation." (PMID 30524437, 2018). "Moreover, the elevated expression of ICAM-1, IL-6, and IL-8 in tEV-treated HUVEC, suggest that EV may translocate these pro-inflammatory mediators and promote vascular endothelial inflammation." (PMID 30131806, 2018). "Moreover, in our previous studies, HDX was also found to exacerbate the MCT-induced pulmonary vascular inflammation, demonstrated by the fact that HDX enhanced NF-κB p65 and ICAM-1 expression in the pulmonary artery endothelial cells in an immunohistochemical study." (PMID 29760703, 2018). "Furthermore, similar to the effects of the miR-146a mimic, IRAK-1 siRNA significantly inhibited the expression of HG-stimulated VCAM-1/ICAM-1 gene expression and THP-1 adhesion to HAECs, indicating that HG-induced endothelial inflammation was mediated partially through IRAK-1." (PMID 28824448, 2017). "Taken together, this indicates that the human ICAM-1 specific antibody 14C11 could prevent airway inflammation in vivo for two major group HRVs, HRV16 and HRV14, but had no non-specific effects on inflammation induced by a stimuli involving human ICAM-1 independent mechanisms." (PMID 23935498, 2013).
cardiovascular disease (91 papers, 2007 to 2026). "Soluble ICAM-1 levels reflect established cardiovascular disease (CVD) risk factors in apparently healthy individuals, highlighting the role of vascular inflammation in disease progression." (PMID 40868926, 2025). "sCD54 is a soluble form of CD54 (ICAM-1) which has been associated with increased cardiovascular disease risk and has been recently used as a marker of chronic inflammation in atherosclerotic plaques." (PMID 32914120, 2020). "The circulating levels of adhesion molecules like vascular cell adhesion molecule-1 (VCAM-1), intercellular adhesion molecule-1 (ICAM-1) and E-selectin are also associated with inflammation and cardiovascular diseases." (PMID 24376824, 2013). "Low concentrations of soluble THBD, especially when present along with elevated soluble ICAM1, predispose to cardiovascular disease (CVD) events." (PMID 17677000, 2007). "A more recent study showed that aldosterone, the level of which correlates with cardiovascular disease severity, induces ICAM-1 expression in arterial endothelial cells in ApoE-deficient mice, and expression is driven largely by activation of the mineralocorticoid receptor." (PMID 37237555, 2023). "Therefore it seems that the mediator between poor sleep (with bad quality and poor sleep recovery) and higher risk for cardiovascular diseases is ICAM-1." (PMID 27738642, 2016). "Elevated levels of ICAM-1 may contribute to cardiovascular disease and are associated with obstructive sleep apnoea (OSA) and obesity, in which sleep deficiency is present." (PMID 27738642, 2016). "In epidemiological studies in a seemingly healthy population, elevated levels of sl ICAM-1 were reported to be associated with an increased risk for the development of cardiovascular disease, periferal vascular disease, carotid artery disease and cerebrovascular stroke." (PMID 27090396, 2016). "In addition, AMD and cardiovascular diseases share common risk factors, including ICAM-1 or VCAM-1 up-regulation." (PMID 25675437, 2015). "Furthermore, parameters that correlated with the levels of indoxyl sulfate (von Willebrand factor, soluble urokinase-type plasminogen activator receptor, soluble intercellular adhesion molecule-1) were positively associated with the prevalence of cardiovascular disease in a CKD patients." (PMID 28122514, 2017). "In cardiovascular disease, IL-38 inhibits inflammation and calcium deposition in aortic valve interstitial cells by inhibiting caspase-1, IL-1, intercellular adhesion molecule-1 (ICAM-1), and vascular cell adhesion molecule-1 (VCAM-1)." (PMID 41596472, 2026). "This meta-analysis aims to evaluate the association between blood ICAM-1 levels and OSA, exploring its potential as a biomarker for cardiovascular disease (CVD) and for identifying factors contributing to result heterogeneity." (PMID 40868926, 2025). "Together, a reduction in PAI- and ICAM1 can contribute to reducing the risks of cardiovascular disease, which highlights the effectiveness of our model of therapy in controlling this outcome." (PMID 38063544, 2023). "In cardiovascular diseases, the anti-inflammatory effects of resveratrol include inhibition of intracellular adhesion molecule 1 (ICAM-1), and induction of nitric oxide synthase (iNOS) and IL-1β mRNA expression in coronary arterial endothelial cells." (PMID 34287272, 2021). "Increased concentrations of sl ICAM-1 were repored in patients with cardiovascular disease, tumors, autoimmune disease and other diseases with an inflammatory reaction." (PMID 27090396, 2016). "Among the adhesion cells that have been proved their role in cardiovascular disease especially in atherosclerosis, are Intercellular adhesion molecule (ICAM)-1, Vascular cell adhesion molecule (VCAM)-1 and E-selectin." (PMID 26687477, 2015). "Soluble VCAM-1 and ICAM-1, adhesion molecules shed by activated endothelial cells, are considered biomarkers of cardiovascular disease." (PMID 23724003, 2013).
cardiovascular disease (continued). "Serum concentrations of proteins associated with risk for cardiovascular disease, including C-reactive protein (CRP), soluble intercellular adhesion molecule-1 (sICAM-1), and leptin, were also measured." (PMID 18775082, 2008). "Among those reported to be independent predictors of cardiovascular disease risk are C-reactive protein (CRP), soluble intercellular adhesion molecule-1 (sICAM-1), and leptin." (PMID 18775082, 2008). "Our study explores the role in cardiovascular disease of four thrombosis genes: coagulation factor V, intercellular adhesion molecule 1, protein C, and thrombomodulin." (PMID 17677000, 2007). "Therefore, since ICAM‐1 is related to the development of cardiovascular diseases, Apigenin, Naringenin, and Vicenin‐2 can be considered cardioprotective in heart diseases involving diabetic animals." (PMID 39055210, 2024). "Moreover, the cardiovascular disease-related risk factors, including ACE2, VCAM-1, and ICAM-1, were significantly higher in patients with PLWH." (PMID 39669584, 2024). "It is not surprising that circulating levels of ICAM1 have previously been associated with cardiovascular disease onset and progression." (PMID 36367600, 2022). "Interestingly, increased levels of endothelial activation markers ICAM-1 and VCAM-1 have been associated with cardiovascular disease in both the uninfected and in the HIV-infected population." (PMID 32575428, 2020). "Air pollution was linked to changes in markers of coagulation (fibrinogen), inflammation (C-reactive protein), and endothelial function (ICAM-1 and VCAM-1), that may influence risk of cardiovascular disease." (PMID 31703266, 2019). "Therefore, identifying novel pharmacological methods to inhibit ICAM-1 expression holds great promise for the prevention of vascular inflammation and cardiovascular diseases." (PMID 28338009, 2017). "Non-invasive in vivo molecular imaging of endothelial ICAM-1 expression could therefore provide valuable insights in the progression of cardiovascular disease-related inflammation to improve diagnosis and treatment." (PMID 22716048, 2012). "Although the relationship between the degree of cellular ICAM-1 and VCAM-1 expression and plasma concentrations of soluble forms is not entirely clear, multiple studies have shown that sICAM-1 and sVCAM-1 predict risk of cardiovascular disease." (PMID 21349799, 2011). "Likewise, ICAM-1 is also involved in cardiovascular disease development." (PMID 38063544, 2023). "VCAM-1 and ICAM-1 are two important members of the immunoglobulin gene superfamily of adhesion molecules, and their potential role as biomarkers of diagnosis, severity and prognosis of cardiovascular disease has been investigated in a number of clinical studies." (PMID 25784313, 2015). "Increased expression of VCAM-1 and ICAM-1 has been shown in SLE tissues such as the skin and heart and high levels of VCAM-1, associated with enhanced systemic TNF-α activity, was recently demonstrated to characterize SLE patients with manifest cardiovascular disease." (PMID 19997561, 2009). "ICAM-1 and VCAM-1’s interaction with NF-kB activation assumes crucial significance in this context, particularly in cardiovascular diseases, where heightened levels of these adhesion molecules exacerbate vascular inflammation and dysfunction." (PMID 39513877, 2024). "Intercellular adhesion molecule-1 is a cell surface glycoprotein expressed by endothelial cells and leukocytes which plays an important role in DKD and cardiovascular disease." (PMID 38672515, 2024). "In cardiovascular disease, the signal transducer and activator of transcription 3 (STAT3) pathway regulated the expression of p21 and ICAM-1 and cryptotanshinone inhibition of STAT3 prevented H19 consumption–mediated p21 induction and delayed aging." (PMID 37805704, 2023).